INS (insulin)
Diseases named in the same sentence as INS in open-access papers (continued):
Sharing a sentence is not in itself a finding about the gene and the disease.
Insulin resistance (continued). "Nevertheless, in instances of significant insulin resistance, GLP-1 receptor agonists, SGLT2 inhibitors, or insulin should be considered." (PMID 40452043, 2025). "Cluster II reflected enhanced cellular proliferation and repair mechanisms, as indicated by elevated cell cycle activity, and also showed signs of insulin resistance and metabolic dysfunction due to reduced PI3K and insulin signaling." (PMID 39941272, 2025). "This study investigates the beneficial effect of LBP on insulin resistance and hepatic glucose production (HGP) in 30 mM glucose induced insulin resistant HepG2 cells (IR-HepG2) and high fat diet/streptozotocin induced diabetic mice." (PMID 40994658, 2025). "However, it is important to acknowledge that while the reversal of the normal cortisol rhythm has been proven to cause insulin resistance, there was not always a direct correlation between changes in cortisol levels and changes in insulin sensitivity after periods of sleep deprivation." (PMID 40786169, 2025). "At week 7 immediately after the two low calorie days of IER, both groups experienced reductions in all fasting measures of insulin resistance i.e. HOMA IR, HOMA-β and fasting insulin." (PMID 41146360, 2025). "Ablation of adipocyte FAM20C also enhanced insulin sensitivity in other metabolic tissues, such as the liver and muscle, placing FAM20C within ATs as a systemic mediator of insulin resistance." (PMID 41148235, 2025). "FAI correlated negatively with markers of obesity (eg, WHR, body fat percentage), insulin resistance, and impaired glycemia (eg, HbA1c, HOMA-IR, insulin), and positively with cell size and basal and insulin-stimulated adipocyte glucose uptake (P < .05)." (PMID 39833659, 2025). "Insulin normally suppresses liver FMO3 expression via phosphoinositide 3-kinase; insulin resistance abrogates this suppression, increasing FMO3 expression and plasma TMAO, positioning TMAO as a liver insulin resistance marker." (PMID 40746564, 2025). "PTP1B came into limelight as a primary target responsible for the progression of abnormal conditions like obesity, insulin resistance, and NAFLD, which is a down-regulator of leptin and insulin pathways." (PMID 40356976, 2025). "These molecular and antioxidant changes were closely linked with improved glycemic parameters, including fasting glucose, glycosylated hemoglobin (HbA1c), homeostatic model assessment for insulin resistance (HOMA-IR), insulin, and C-peptide." (PMID 40867832, 2025). "Given the insulin resistance and impaired insulin secretion observed in PTDM patients—often exacerbated by immunosuppressive agents—exogenous insulin remains a cornerstone for effective glycemic management in this population." (PMID 40995094, 2025). "Women with gestational-IFG had greater insulin resistance (HOMA-IR 3.11 vs 2.25, P = .001) and decreased insulin sensitivity (HOMA-IS 0.39 vs 0.43, P = .001)." (PMID 39446494, 2025). "To assess insulin resistance in WT and OPA1+/− mice, we measured plasma insulin concentrations and calculated the Homeostatic Model Assessment of Insulin Resistance (HOMA-IR) before and after HFD exposure." (PMID 40722980, 2025). "These patterns highlight how insulin secretion adapts to metabolic demands, emphasizing the need to interpret HOMA-B changes within the context of insulin resistance." (PMID 40843316, 2025). "These free fatty acids accumulate in peripheral tissues and disrupt the insulin signaling pathway through the activation of pathways such as protein kinase C and JNK, leading to impaired glucose uptake and insulin resistance." (PMID 40678778, 2025). "DAG contributes to insulin resistance in T2D by activating PKC, which disrupts insulin signaling pathways." (PMID 41393296, 2025). "Glucose tolerance test (GTT), insulin tolerance test (ITT) and modified homeostatic model assessment for insulin resistance (HOMA‐IR, 5‐h fasting) were used to evaluate glucose metabolism." (PMID 41208560, 2025).
Insulin resistance (continued). "The Homeostatic Model Assessment of Insulin Resistance (HOMA-IR), based on fasting glucose and insulin levels, is commonly used to evaluate IR." (PMID 41195424, 2025). "Similarly, insulin, secreted by pancreatic β cells, acts on hypothalamic neurons to regulate glucose metabolism and satiety; however, it was often observed that obesity led to hypothalamic insulin resistance, characterised by impaired insulin signalling and impaired glucose uptake in the brain." (PMID 41226484, 2025). "mTORC1 hyperactivation can lead to insulin resistance through multiple mechanisms, including the phosphorylation of IRS-1 and the regulation of insulin signaling via Grb10." (PMID 40141237, 2025). "Insulin levels and HOMA-IR scores were significantly elevated in the HFHFr group (p < 0.05), indicating insulin resistance, while both doses of AAL and OMT significantly lowered these markers (p < 0.001)." (PMID 41029678, 2025). "We performed glucose tolerance and insulin tolerance test on mice treated with PBS or MEV for 5 weeks, which revealed that MEV administration induced mild but significant insulin resistance and glucose intolerance." (PMID 40484172, 2025). "The homeostatic model assessment (HOMA) was used to assess insulin secretion (HOMA-beta) and insulin resistance (HOMA-IR)." (PMID 41041632, 2025). "The IF, but not the HL control group, had significant reductions in fasting plasma insulin levels, insulin resistance (HOMA2-IR), HbA1c (an index of chronic glycemic control), and neuronal insulin resistance." (PMID 40805992, 2025). "GDM patients with the GG genotype have higher levels of fasting blood glucose, fasting insulin, and HOMA-insulin resistance." (PMID 41488068, 2025). "Insulin levels and HOMA-IR were markedly higher in the PCOS group (p < 0.001), confirming insulin resistance, whereas metformin and thymoquinone significantly lowered these values (p < 0.01), with metformin showing a slightly stronger effect." (PMID 41010765, 2025). "The homeostasis model assessment of insulin resistance (HOMA-IR) score was calculated via glucose and insulin data for all the groups." (PMID 40162234, 2025). "Modulation of this pathway can be monitored through measurement of fasting serum insulin, IGF-1, and IGFBP-3 levels, as well as by evaluating insulin resistance indices, such as the homeostatic model assessment for insulin resistance (HOMA-IR)." (PMID 41008741, 2025). "Metformin, as an insulin sensitizer, reduces insulin resistance and hyperinsulinemia, which is commonly used in the treatment of PCOS with insulin resistance." (PMID 41384017, 2025). "The glucose tolerance test and insulin tolerance test results indicated that HFD impaired glucose tolerance and insulin sensitivity, resulting in insulin resistance." (PMID 41317904, 2025). "Our in-depth analysis has emphasized the central importance of insulin resistance and metabolic disturbances in the pathogenesis of DCM, shedding light on the complex interplay between insulin signaling genes and cardiac dysfunction." (PMID 40747301, 2025). "Further analysis of serum insulin levels showed that insulin levels and HOMA-IR were significantly elevated in the db/db model group compared to the normal C57BL/6J group, indicating hyperinsulinemia and insulin resistance." (PMID 40430283, 2025). "In obesity and type 2 diabetes mellitus (T2DM), insulin cannot suppress glucose production in the liver, and a condition called T2DM characterized by insulin resistance occurs." (PMID 41417360, 2025). "Central to its progression are altered cellular signaling pathways, such as the insulin/PI3K/Akt pathway, which regulates glucose uptake and lipid metabolism and is commonly impaired in insulin resistance." (PMID 40868165, 2025). "In particular, differences in CRP, insulin, and HOMA-IR levels were significantly elevated in the obesity group, indicating a potential increase in systemic inflammation and insulin resistance (p = 0.001)." (PMID 41374089, 2025).
Insulin resistance (continued). "In addition, experimental studies have shown that direct exposure of insulin-sensitive cells to lactate induces insulin resistance, suggesting that the metabolic reprogramming induced by SARS-CoV-2 may play a significant role in the onset or exacerbation of T2DM." (PMID 40564201, 2025). "For instance, it inhibits the expression of key genes in the insulin signaling pathway, such as IRS-2, PI3K, and Akt, leading to insulin resistance." (PMID 40129979, 2025). "Derived indices included a free androgen index (FAI), homeostasis model assessment of insulin resistance (HOMA-IR), and fasting glucose-to-insulin ratio." (PMID 40807164, 2025). "It was negatively correlated with the index of insulin resistance (HOMA-IR), and also with basal insulin levels (r = −0.354, p = 0.04 and r = −0.343, p = 0.04, respectively)." (PMID 40806137, 2025). "The significantly higher fasting insulin levels (18.5 ± 4.3 vs. 12.6 ± 3.8 μU/mL, p<0.001) and HOMA-IR (4.5 ± 1.2 vs. 2.8 ± 0.9, p<0.001) in obese PCOS women indicate profound insulin resistance." (PMID 40792318, 2025). "The homeostasis model assessment of insulin resistance (HOMA-IR) was introduced in 1985 and is used to quantify insulin resistance (IR) and beta-cell function using basal glucose and insulin concentrations." (PMID 40018272, 2025). "Hence, future research should address and elucidate the signaling pathways by which FFARs mediate the effects of fatty acids on insulin secretion and lipotoxicity, which could lead to new therapeutic strategies for managing insulin resistance and related metabolic disorders." (PMID 39859502, 2025). "The HOMA-IR, an index of insulin resistance, demonstrated that BBE treatment markedly improved insulin sensitivity." (PMID 40362407, 2025). "These mediators disrupt insulin signaling through JNK and NF-κB pathway activation, leading to systemic insulin resistance, cardiovascular complications, gut dysbiosis and other metabolic disorders." (PMID 40699756, 2025). "Levels of fasting insulin and C-peptide were also higher in the DKD group, indicating more severe insulin resistance in DKD patients." (PMID 41140685, 2025). "In addition, insulin resistance is related to the increase of free fatty acid and reactive oxygen species levels and the onset of dyslipidemia, which will lead to oxidative stress and the release of proinflammatory cytokines, damage insulin signal transduction, and accelerate atherosclerosis." (PMID 40235659, 2025). "It should be noted that there were the increasing trends of some insulin sensitivity indices overtime including relative plasma C-peptide level, pancreatic beta-cell function index (HOMA-beta), and insulin resistance index (HOMA-IR)." (PMID 39883721, 2025). "Fasting metabolic markers, including triglycerides, Homeostatic Model Assessment for Insulin Resistance (HOMA-IR; calculated using fasting blood glucose and insulin levels), LDL-C, and high-density lipoprotein cholesterol (HDL-C), were evaluated." (PMID 41294355, 2025). "This was accompanied by elevated ER stress markers and impaired insulin signaling, as evidenced by the reduced phosphorylation of IRS1 and Akt, contributing to insulin resistance." (PMID 39942544, 2025). "Insulin resistance in cystic fibrosis patients serves as an important contributing factor to CFRD development, in addition to insulin secretion defects." (PMID 41300682, 2025). "In differentiated SH-SY5Y cells treated with STZ, a rightward shift in the dose-response curve of insulin-induced GSK-3 phosphorylation was observed, which suggests the beginning of insulin resistance." (PMID 39932549, 2025). "As a key negative regulator within the insulin signaling pathway, modulating the activity of PTP1B contributes to the alleviation of insulin resistance." (PMID 40278263, 2025).
Insulin resistance (continued). "Some previous studies reported that EPO treatment improved glucose tolerance in high-fat diet-induced obesity and insulin-resistant model animals, suggesting the possibility that EPO is a novel therapeutic agent for insulin resistance." (PMID 40943240, 2025). "In the early phase of insulin resistance, increased IGF-1 levels coincide with augmented insulin synthesis, leading to compensatory hyperinsulinemia." (PMID 41514592, 2025). "Further analyses were conducted to assess insulin resistance and β-cell function, including Insulin HOMA-IR, C-peptide HOMA2-%B, fasting insulin, and proinsulin levels." (PMID 40755872, 2025). "QUICKI reflects overall insulin sensitivity, while HOMA-IR indicates the extent of insulin resistance." (PMID 41011571, 2025). "In insulin resistance, the expression of glucose transporter 4 (GLUT4) is down-regulated in adipocytes, leading to impaired insulin-stimulated glucose transport and worsening glucose intolerance." (PMID 40951890, 2025). "Prevotella copri is a dominant species within the genus Prevotella, which is more abundant in patients with insulin resistance and T2DM, leading to a decrease in insulin sensitivity through promoting BCAAs synthesis." (PMID 41357863, 2025). "Excess iron, by catalyzing ROS through the Fenton reaction, enhances the OS that interferes with insulin signaling cascades (mTOR, NF-κB, PKC, JNK activation, IRS1 tyrosine reduction, increased serine phosphorylation), resulting in insulin resistance." (PMID 39941760, 2025). "In contrast, progesterone promotes insulin resistance, possibly through interference with insulin receptor signaling and impaired GLUT4 translocation, necessitating greater insulin secretion from β-cells to maintain glucose homeostasis." (PMID 40076938, 2025). "HCV core protein can mediate serine phosphorylation of IRS1 to facilitate insulin resistance as well as upregulate SOCS3 and SOCS7, which are known insulin inhibitors." (PMID 41012578, 2025). "Various indices have been used in clinical practice to assess insulin resistance, including the Homeostasis Model Assessment for Insulin Resistance (HOMA-IR) and the Quantitative Insulin Sensitivity Check Index (QUICKI)." (PMID 40361947, 2025). "The pro-inflammatory cytokine IL-6 contributes to insulin resistance through serine/threonine phosphorylation of IRS-1, thereby disrupting insulin signal transduction." (PMID 40959695, 2025). "Further, insulin resistance was also estimated with the HOMA2-IR calculator using fasting glucose and plasma insulin; values were ~1.8 after 10 weeks on HFD alone compared to ~3 post-STZ injections." (PMID 41002949, 2025). "OC-/- mice on a mixed 129/BL6 background displayed significant glucose intolerance (GTT), insulin resistance (ITT), increased fat pad mass/BW, reduced insulin secretion (GSIS) and β-cell proliferation compared to WT mice." (PMID 41516047, 2025). "There is a record that the insulin signaling suppression induced by lipids through IRS-1 and IRS-2 is responsible for peripheral insulin resistance." (PMID 39859069, 2025). "In diabetic animals,insulin resistance (HOMA-IR index) increased (p <0.0001) due to increased serum glucose levels, while beta cell function(HOMA-β index) and insulin sensitivity index (p < 0.0001) decreased compared to the control group." (PMID 40547654, 2025). "Simultaneously elevated insulin and CRH actions at the level of the hepatocyte produce the early stage phenotype of insulin resistance." (PMID 40421040, 2025). "Insulin plasma levels and the HOMA‐IR index, indicators of insulin resistance, were similar to the control group in green tea‐treated mice compared to the elevated levels observed in the HFD‐fed mice." (PMID 40522107, 2025). "In contrast, 3 days of KD induced more pronounced hepatic insulin resistance in mice versus HFD-feeding, as revealed by impaired insulin-mediated suppression of hepatic glucose production despite normal glucose uptake in peripheral tissues." (PMID 40864559, 2025).
Insulin resistance (continued). "Across the overall group, lower Mg levels were strongly correlated with higher glucose (R = −0.58) and HbA1c levels (R = −0.61), as well as increased insulin resistance (HOMA-IR: R = −0.28) and decreased insulin sensitivity (QUICKI: R = 0.30)." (PMID 39833091, 2025). "Insulin resistance induces the production and activation of TNF-α, resulting in the massive release of insulin and insulin-like growth factors (IGFs)." (PMID 40299397, 2025). "In humans with insulin resistance, GLUT4 is mislocalized during fasting, so that it is depleted from insulin-responsive intracellular membranes." (PMID 40631311, 2025). "Biochemical variables, triglyceride (TG), high‐density lipoprotein cholesterol (HDL‐C), apolipoprotein A1 (ApoA1), apolipoprotein B (ApoB), fasting serum insulin (FINS), and homeostatic model assessment of insulin resistance (HOMA‐IR) were determined." (PMID 41323197, 2025). "The results showed that insulin resistance was improved after treatment with AGOM and PIO, as demonstrated by the reduction in fasting plasma glucose, insulin, and HOMA-IR." (PMID 40076566, 2025). "In obesity, where oxidative stress typically derails insulin signaling, anthocyanins’ ability to enhance PI3K/Akt activation provides a potential therapeutic intervention for glucose metabolism improvement and insulin resistance relief." (PMID 40218884, 2025). "It impacts insulin signaling via the Toll-like receptor 4 and monocyte differentiation antigen CD14 pathway, resulting in insulin resistance." (PMID 39860434, 2025). "The pooled data showed that probiotics significantly reduced fasting blood glucose (SMD = −0.40), insulin levels (SMD = −0.57), and insulin resistance (SMD = −0.64) while increasing the quantitative insulin sensitivity check index (QUICKI) (SMD = 0.58)." (PMID 40255841, 2025). "Enhances glucose uptake, stimulates mitochondrial biogenesis, improves insulin sensitivity, regulates glucose metabolism through AMPK signaling, and reduces insulin resistance." (PMID 39963239, 2025). "The oral glucose tolerance test (OGTT) showed obvious glucose intolerance in the FTPA group, and the FPI values and insulin tolerance test (ITT) were both significantly elevated in the FTPA group, indicating insulin resistance." (PMID 40878918, 2025). "We then examined the correlation between FAM20C expression and various metabolic parameters, including body weight, BMI, body fat percentage, fasting plasma insulin (FPI), homeostasis model assessment of insulin resistance (HOMA-IR), and HbA1c." (PMID 41148235, 2025). "Alternative markers, such as fasting plasma insulin (FPI) and the homeostasis model assessment of insulin resistance (HOMA-IR), are used to assess glycemic control and insulin sensitivity." (PMID 40861555, 2025). "Reduced expression of insulin signalling pathway genes in patients with insulin resistance (INSR, AKT, PIK3R1, IRS2) indicates a diminished insulin response in both VAT and SAT." (PMID 40806527, 2025). "ADIPOQ and TNFA increase insulin sensitivity and insulin resistance, respectively, through modulation of phosphorylation and activation of IRS-1 (a molecule determining insulin sensitivity2930,31." (PMID 41193585, 2025). "Overweight and obese children had higher fasting insulin levels, and obese children had the highest HOMA-IR values, indicating insulin resistance." (PMID 40641901, 2025). "Higher baseline fitness also appeared to enhance glucose response, which is supported by mechanistic studies showing that regular PA improves insulin action by increasing GLUT4 expression and reducing insulin resistance." (PMID 41059660, 2025). "After four weeks, the DASH diet group showed significant improvements compared with the GC: FPG decreased by 7.62 mg/dL, serum insulin levels decreased by 2.62 μIU/mL, and the HOMA-IR score (a marker of insulin resistance) decreased by 0.8." (PMID 40430185, 2025).